CD180 (CD180 molecule)
Diseases named in the same sentence as CD180 in open-access papers (continued):
Sharing a sentence is not in itself a finding about the gene and the disease.
glioma (1 paper, 2024). A benign or malignant brain and spinal cord tumor that arises from glial cells (astrocytes, oligodendrocytes, ependymal cells). "Especially, the expression level of CD180 was associated with macrophage infiltration level in glioma." (PMID 39707188, 2024). "The immune characteristics of CD180 revealed its significant association with immune cell infiltration in gliomas." (PMID 39707188, 2024). "It showed that the elevated CD180 expression in gliomas was associated with more aggressive clinical subgroups, suggesting its role in tumor malignancy." (PMID 39707188, 2024). "It implies a potential association between CD180 expression and specific genetic alterations that propel glioma progression." (PMID 39707188, 2024). "CD180 was significantly upregulated in glioma samples and associated with poor prognosis." (PMID 39707188, 2024). "CD180-overexpression macrophages enhanced glioma cell proliferation, migration, and invasion while reducing apoptotic capacities." (PMID 39707188, 2024). "As our study relies on co-culture systems, we have provided a mechanistic insight into the interaction between CD180-overexpression macrophages and glioma cells." (PMID 39707188, 2024). "Analysis of scRNA-seq data revealed the predominant expression of CD180 in macrophages within the glioma TME." (PMID 39707188, 2024). "The results of scRNA-seq analysis confirmed that CD180 was concentrated in macrophages within gliomas." (PMID 39707188, 2024). "In glioma cell lines co-cultured with CD180-transfected macrophages, the apoptosis ability is significantly reduced." (PMID 39707188, 2024). "This study revealed the association between CD180 expression and unfavorable clinical outcomes in gliomas, highlighting CD180 as a potential prognostic biomarker." (PMID 39707188, 2024). "In this study, we found that CD180 was significantly upregulated in gliomas at both RNA and protein levels." (PMID 39707188, 2024). "Transwell migration and invasion assays were performed to evaluate cellular behavior, and the results showed significantly enhanced ability of migration and invasion of glioma cell lines after co-cultured with CD180-transfected macrophages (P < 0.05)." (PMID 39707188, 2024). "We co-cultured three glioma cell lines with CD180-overexpression macrophages to assess the effects on glioma cell proliferation, migration, invasion, EMT, and apoptosis." (PMID 39707188, 2024). "We identified nine chemotherapeutic agents that were more effective in glioma patients with high CD180 expression." (PMID 39707188, 2024). "Based on TIMER database, we found that CD180 was positively correlated with the infiltration level of immune cells in glioma." (PMID 39707188, 2024). "In vitro experiments demonstrated that CD180-overexpression macrophages promoted glioma cell proliferation, migration, invasion, and epithelial-mesenchymal transition (EMT), while decreasing apoptosis." (PMID 39707188, 2024). "It showed that glioma patients with high CD180 expression correlated with a significantly shorter OS (P < 0.05 for all)." (PMID 39707188, 2024). "Then the CD180-transfected macrophages were co-cultured with glioma cell lines including U87, U251 and LN229." (PMID 39707188, 2024). "We performed in vitro experiments to elucidate the role of CD180-overexpression macrophages within the glioma microenvironment." (PMID 39707188, 2024). "The results demonstrated a significantly worse prognosis for cluster 2 compared to cluster 1, highlighting the prognostic significance of CD180 in gliomas." (PMID 39707188, 2024). "This study confirmed the prognostic role of CD180 in glioma and its involvement in immunosuppressive regulation and malignant phenotype promotion." (PMID 39707188, 2024). "The validation of these findings across multiple datasets underscored the robustness of CD180 as a prognostic biomarker in gliomas." (PMID 39707188, 2024).
glioma (continued). "Cox regression identified CD180 as an independent prognostic factor for glioma patients (HR = 1.454, 95%CI = 1.046–2.020, P = 0.026)." (PMID 39707188, 2024). "To explore the impact of CD180 in tumor heterogeneity, we classified the glioma samples into two distinct CD180-related glioma subtypes." (PMID 39707188, 2024). "It suggested the therapeutic potential of these drugs in the treatment of glioma with high CD180 expression." (PMID 39707188, 2024). "Moreover, we identified DEGs between different CD180 expression groups and classified glioma samples into two CD180-related subtypes." (PMID 39707188, 2024). "The scRNA-seq revealed that CD180 was primarily expressed in macrophages of glioma samples." (PMID 39707188, 2024). "The significant enhancement in cellular behaviors promoted tumor aggressiveness, so CD180 could be a potential therapeutic target for gliomas." (PMID 39707188, 2024). "It showed that CD180 significantly increased with the grades of glioma." (PMID 39707188, 2024). "We identified potential chemotherapeutic agents that might be effective in gliomas with high CD180 expression." (PMID 39707188, 2024). "CD180 might exert protective effects on glioma cells at an early stage of the apoptotic pathway, due to the early apoptotic events were predominantly reduced." (PMID 39707188, 2024). "CD180-overexpression macrophages were co-cultured with three glioma cell lines." (PMID 39707188, 2024). "Therefore, CD180 was considered as a promising target for immunotherapeutic strategies in glioma treatment." (PMID 39707188, 2024). "RNA-seq data were obtained to analyze CD180 expression in gliomas and assess its prognostic value." (PMID 39707188, 2024). "Subsequently, we validated the expression of CD180 using qRT-PCR in an independent glioma group." (PMID 39707188, 2024). "The elucidation of this molecular shift provided a plausible pathway, through which CD180-overexpression macrophages might facilitate glioma progression." (PMID 39707188, 2024). "Additionally, our investigation also delved into the role of CD180 in immunosuppressive regulation and malignant phenotype promotion in glioma." (PMID 39707188, 2024). "High CD180 expression was correlated with a worse prognosis in glioma patients." (PMID 39707188, 2024). "Consensus clustering was used to identify CD180-related glioma subtypes." (PMID 39707188, 2024). "Additionally, two CD180-related glioma subtypes with distinct prognosis were identified." (PMID 39707188, 2024). "Therefore, we further explored the prognostic value of CD180 in glioma." (PMID 39707188, 2024). "Furthermore, drug sensitivity analysis identified several chemotherapeutic agents that could potentially exhibit enhanced efficacy in gliomas with high CD180 expression, thereby emphasizing promising strategies for chemotherapy." (PMID 39707188, 2024). "Moreover, we identified the top 9 common chemotherapeutic agents that glioma patients with high CD180 expression might be sensitive." (PMID 39707188, 2024). "It showed that CD180 was predominantly expressed in macrophages, suggesting an immunosuppressive effect in the TME of gliomas." (PMID 39707188, 2024). "Specifically, we propose that CD180 overexpression in macrophages may affect the secretion of immunomodulatory cytokines (e.g., IL-10, TGF-β) that suppress anti-tumor immunity and promote glioma cell proliferation." (PMID 39707188, 2024). "However, no studies have yet investigated the role of CD180 in gliomas, indicating a critical area for future research." (PMID 39707188, 2024).
HCMV infection (1 paper, 2021). "Altogether, we decided on three hit candidate receptors: CD164, which was downregulated from the surfaces of all cells analyzed, and CD84 and CD180, which seem to be myeloid cell-specific receptors with reduced expression upon HCMV infection." (PMID 34399625, 2021).
IgG4-related disease (1 paper, 2023). "Some patients with IgG4-related disease (IgG4-RD) also present with CD180-negative B cells and loss of CD180 corresponded with increased disease activity in IgG4-RD." (PMID 37460961, 2023).
lymphocytic leukemia (1 paper, 2022). "CD180 was identified as a pharmacodynamic biomarker for tumors especially in lymphocytic leukemia." (PMID 36035315, 2022).
mantle cell lymphoma (1 paper, 2023). Mantle cell lymphoma is a rare form of malignant non-Hodgkin lymphoma affecting B lymphocytes in the lymph nodes in a region called the ``mantle zone''. "Using flow cytometry, it was shown that CD180 was weakly expressed by malignant cells in chronic lymphocytic leukemia (CLL), mantle cell lymphoma and lymphoplasmacytic lymphoma, compared with control B cells." (PMID 37460961, 2023). "Other combinations of markers used in conjunction with CD180, such as CD148 and CD200 or CD148 alone, have been suggested to be useful for distinguishing MZL from other malignancies such as mantle cell lymphoma (MCL)." (PMID 37460961, 2023).
marginal zone lymphoma (1 paper, 2023). A usually indolent mature B-cell lymphoma, arising from the marginal zone of lymphoid tissues. "The level of expression of CD180 in hairy cell leukemia, marginal zone lymphoma (MZL), follicular lymphoma (FL) and splenic diffuse red pulp small B cell lymphoma was found to be comparable to that of control B cells." (PMID 37460961, 2023).
Mycobacterium avium infection (1 paper, 2023). "For example, CD180 expression by murine macrophages does not increase in response to Mycobacterium avium infection." (PMID 37460961, 2023).
myocardial infarction (1 paper, 2023). Gross necrosis of the myocardium, as a result of interruption of the blood supply to the area, as in coronary thrombosis. "Furthermore, a recent study also implicated CD180-mediated inactivation of TLR2 as a potential pathway which promotes cardiac repair following myocardial infarction." (PMID 37460961, 2023). "WT mice develop significantly worse cardiac damage following myocardial infarction compared to mice where CD180 was overexpressed in murine cardiac tissue by adenovirus transfection, suggesting that CD180 plays a protective role in cardiac injury." (PMID 37460961, 2023).
Parkinson’s (1 paper, 2017). "Altered expression of CD180 has been reported in peripheral blood leukocytes of Parkinson’s patients and it is significantly dysregulated during cortical-striatal circuit dysfunction." (PMID 28792504, 2017).
Splenomegaly (1 paper, 2018). Abnormal increased size of the spleen. "Compared with control C57BL/6 mice, IgG2b-treated MRL/lpr mice displayed marked splenomegaly, while splenomegaly was significantly reversed in anti-CD180 Ab-treated MRL/lpr mice." (PMID 30498494, 2018). "Imiquimod could induce marked splenomegaly in IMQ-mice, while imiquimod-induced splenomegaly was significantly reversed in anti-CD180 Ab-treated IMQ-mice." (PMID 30498494, 2018).
infection (7 papers, 2013 to 2024). The state of being infected such as from the introduction of a foreign agent such as serum, vaccine, antigenic substance or organism. "Additionally, CD180, an inducer of B cell proliferation, activation and differentiation, was uncovered to be up-regulated all along infection." (PMID 24308825, 2013). "After 48 h of infection, the levels of TNF, CXCL8, IL6, CSF2, CD180, CD14, and CCL2 levels increased and those of IL-10, INFB1, and CXCL10 decreased." (PMID 36296238, 2022). "(G) Infection leads to little or no change in CD180 and CD206 immunostaining in macrophages in the leptomeninges." (PMID 37318981, 2023). "Administration of a WNV E-anti-CD180 conjugate vaccine 30 days prior to WNV infection induced Ab responses that protected against lethal infection in BAFFR-/- mice but not in μMT mice." (PMID 29176765, 2017). "The negative effect which CD180 has on classical TLRs suggests that CD180 may become upregulated in response to infection to aid prevention of hyperinflammation." (PMID 37460961, 2023). "Infection also led to a reduction in LYVE1 abundance, but little or no change in CD180 or CD206 abundance, in macrophages." (PMID 37318981, 2023). "As the role of M. hominis in the modulation of Rab7, TLR9, and CD180 has not been reported, additional studies are necessary to elucidate the M. hominis–PHK interaction in the infection process." (PMID 36296238, 2022).
tumor (6 papers, 2020 to 2024). "Furthermore, CD180 is significantly upregulated in tumor-associated macrophages (TAMs)." (PMID 39707188, 2024). "The expression level of CD180 was first investigated in pan-cancer, and it showed that CD180 exhibited significantly higher expression levels in tumor samples compared to normal tissues for most cancer types." (PMID 39707188, 2024). "Additionally, they report stimulation of CD180 by LPS secreted from the tumor microenvironment leads to MM growth." (PMID 34864816, 2021). "ESTIMATE analysis showed that CD180 was significantly positively correlated with stromal score, immune score, and ESTIMATE score, but negatively correlated with tumor purity, suggesting the potential role of CD180 in TME." (PMID 39707188, 2024). "CD180 is a LPS receptor similar to Toll-like receptor 4 (TLR4) and is reported to promote oncogenesis and tumor growth." (PMID 34864816, 2021). "CD180, as well as CCR2, has been identified as robust pharmacodynamic tumor and blood biomarkers for clinical use with BRD4/BET inhibitors." (PMID 33082842, 2020). "The positive correlation between CD180 expression and immune scores and stromal score, alongside the negative correlation with tumor purity, also suggested the potential role of CD180 in shaping TME." (PMID 39707188, 2024). "Compared to macrophages cultured without tumor cell contact, CD180 expression was significantly upregulated in TAMs." (PMID 39707188, 2024). "The upregulation of immune checkpoints in high CD180 expression groups implied that CD180 might contribute to an immunosuppressive TME, which could facilitate immune evasion by tumor cells." (PMID 39707188, 2024). "Taken together, these data suggest that through studying CD180 expression and activation, it may be possible to better predict and explain the observed heterogeneity in CLL tumor aggressiveness, progression, and therapy responsiveness." (PMID 37460961, 2023). "CD180 was not uniquely expressed by B cells but was also expressed in tumor tissues." (PMID 35634306, 2022). "In addition to CD180, chemokine receptor type 2 (CCR2) mRNA levels were downregulated in response to AZD5153 treatment, thus BRD4 inhibition may modulate the transmigration of tumor cells within the microenvironment." (PMID 37460961, 2023).
cancer (5 papers, 2017 to 2024). A tumor composed of atypical neoplastic, often pleomorphic cells that invade other tissues. "TREM2 and CD180 are negative regulators of the Toll-like receptor pathway, a family of receptors that recognize damage-associated molecule patterns, whose increased serum levels have been associated with cancer." (PMID 28927421, 2017). "Functional studies using primary cells and immortalized cell lines have indicated that CD180 plays a significant role in the immunopathology of these cancers." (PMID 37460961, 2023). "Therefore, it is possible that CD180 may also be of value for predicting outcomes in these cancers." (PMID 37460961, 2023).
hematological cancer (1 paper, 2023). "When a range of hematological cancer cell lines, including ALL, MM, and DLBCL types, were treated with AZD5153, a novel BRD4 inhibitor, all demonstrated considerable reduction in CD180 mRNA levels." (PMID 37460961, 2023).
hematological malignancies (1 paper, 2023). "Together, these data suggest that CD180 mRNA levels may be a relevant pharmacodynamic biomarker for BRD4 inhibitors in hematological malignancies." (PMID 37460961, 2023).
CD180 also shares sentences with these, for which no sentence is quoted: systemic sclerosis (3 papers); autoimmune (2); B cell lymphoma (1); B-cell neoplasm (1); bacterial infections (1); dermatomyositis (1); hairy cell leukemia (1); Kawasaki disease (1); leukemia (1); multiple sclerosis (1); Myasthenia (1); nephritis (1); Neurologic Disease (1); Obesity (1); overnutrition (1); Respiratory tract infection (1); rheumatic diseases (1); rheumatoid arthritis (1).